PPIAP15 (peptidylprolyl isomerase A pseudogene 15)
Synonyms: formerly PPIP5
Gene: Processed pseudogene on chromosome 3 (109,471,329 to 109,471,812, reverse strand). Ensembl gene ENSG00000244196.
Diseases named in the same sentence as PPIAP15 in open-access papers:
PPIAP15 is named in the same sentence as 3 diseases in open-access papers, as found by Europe PMC text mining. Sharing a sentence is not in itself a finding about the gene and the disease.
PPIAP15 shares sentences with these, for which no sentence is quoted: infection (2 papers); cancer (1); fungal infection (1).